INS (insulin)
Diseases named in the same sentence as INS in open-access papers (continued):
Sharing a sentence is not in itself a finding about the gene and the disease.
diabetes (continued). "The hyperglycemia in type 2 diabetes mellitus (T2DM) results from an imbalance between insulin secretion and insulin sensitivity with impaired insulin action and an insufficient and delayed insulin response during meals as well as an inappropriate glucagon secretion." (PMID 31164926, 2019). "VARC-2-defined device success was achieved in 89.5% of patients without diabetes, 89.4% of patients with orally treated diabetes and 88.8% of patients with insulin-treated diabetes (p = 0.944)." (PMID 31138207, 2019). "Of particular note is the association found between serum levels of sCD163 and glycemia-related variables (insulin, HOMA-IR index and fasting glycemia), corroborating previous findings for this biomarker in the context of diabetes and altered glucose metabolism." (PMID 31500625, 2019). "Then diabetes PI3K/AKT pathway was activated in GDM (due to increased insulin level) yet did not translate to improved glycemic effect, suggesting the incidence of IR." (PMID 31287224, 2019). "The median plasma NT‐proBNP concentration was highest in insulin‐treated individuals (581 pg/mL) and lowest in those without diabetes (364 pg/mL), with an intermediate level in patients with diabetes not treated with insulin (430 pg/mL)." (PMID 31271255, 2019). "Approximately 12.0% of people with diabetes were not undergoing treatment for diabetes, and 80.0% and 8.0% were treated with an oral hypoglycemic agent and insulin, respectively." (PMID 30974788, 2019). "When used in tandem with other forms of diabetes medications (specifically sulfonylureas), 5-ALA is expected to stimulate insulin sensitivity in patients who are deemed “insulin resistant” (continuous high HbA1c levels) by enhancing glucose metabolism in the TCA cycle." (PMID 31781665, 2019). "Evidences connecting AD to impaired function of insulin/IGF suggested AD might be viewed as a new type, “type 3,” of diabetes." (PMID 31404401, 2019). "Since diabetes is not usually diagnosed until several years after the appearance of insulin and glucose deregulation, it is crucial to detect the early stages of the disease through the use of adequate biomarkers of reduced insulin sensitivity." (PMID 31208038, 2019). "Previous studies have supported the effectiveness of mHealth interventions for diabetes self-management; however, there are no mobile programs to assist patients with type 2 diabetes with the process of insulin titration." (PMID 31368439, 2019). "This is our hypothesis that the intestinal cells transiently produce insulin with the help of GLP 1 as an adaptive mechanism, against stress before the onset of diabetes." (PMID 31380261, 2019). "This intriguing brain-to-body metabolism and diabetes link was not intensely studied as the discovery of insulin in 1923 subsequently dominated the diabetes field." (PMID 31024226, 2019). "At the fifteenth month, when the diabetes model was successfully implemented, diabetic pigs (7/13) exhibited significant increases in weight, GLU, TCH, TG, and LDL; concomitantly, they showed significant reductions in INS and HDL." (PMID 31088378, 2019). "Insulin is needed to regulate blood glucose levels, and diabetes mellitus results from the lack of glucose regulation." (PMID 31781665, 2019). "Since there is no specific cure for diabetes, daily glycemic measures need to be carried out together with active treatments (insulin injection or bariatric surgery) to improve diabetic patients’ quality of life." (PMID 30866459, 2019). "Diabetes is a chronic disease marked by high level of blood glucose that occurs either when the pancreas does not produce enough insulin or when the body cannot effectively use the insulin that was produced." (PMID 31783906, 2019). "Participants disclosed and discussed their struggles with diabetes self-care surrounding discipline, lack of education, fear related to glucose monitoring and injecting insulin, financial difficulties, and time limitations." (PMID 31723504, 2019).
diabetes (continued). "The development of radioimmunoassays for insulin, proinsulin and its cleaved section C-peptide, only tended to confirm that children with diabetes had little or no insulin, while adults often had substantial amounts." (PMID 31558146, 2019). "It has been observed that heterozygous mice expressing non-phosphorylable eIF-2α (Ser51 substituted by an alanine) developed diabetes when fed an HFD and had severely impaired insulin secretion and a defective trafficking of pro-insulin which accumulated within the ER lumen." (PMID 30987118, 2019). "Patients with diabetes, regardless of insulin use, had a higher prevalence of myocardial infarction, hypertension and stroke than patients without diabetes." (PMID 31271255, 2019). "Type 2 diabetes mellitus (T2DM) is a heterogeneous metabolic disease characterized by hyperglycaemia due to insulin resistance in adipose tissue, muscle, and liver and/or impaired insulin secretion by pancreatic β-cells." (PMID 31018536, 2019). "Although none developed diabetes, elevated baseline insulin levels, indicative of the onset of insulin resistance, were positively associated with high baseline levels of GRP94 (not shown)." (PMID 30733237, 2019). "Some cardiac alterations appear in the early stage of diabetes mellitus: Impairment of insulin-related pathways, increase in non-esterified fatty acids (NEFAs), lipotoxicity in myocardial tissue, and mitochondrial dysfunctions." (PMID 31690052, 2019). "Taken together, these findings strongly suggest that the pathways related to insulin signaling rather than blood glucose levels play a key role in the development of cognitive impairment in the natural history of diabetes." (PMID 31835729, 2019). "Data on exogenous insulin therapy in our study participants were not available, although we did assess current use of diabetes medications." (PMID 31065243, 2019). "The controversy persists, and there is not enough evidence to justify the universalization of insulin analogs as the standard therapy for all pregnant women with diabetes." (PMID 30786308, 2019). "Diabetes mellitus is a chronic disease, which occurs in the pancreas that does not generate enough insulin or of which cells do not reply to insulin that is produced." (PMID 32184850, 2019). "Both the control (standard diabetes diet, no sardines) and the sardine group (standard diabetes diet +100 g sardines/d) reduced fasting insulin concentration and homeostasis model of assessment insulin resistance (HOMA-IR) to comparable levels." (PMID 30728086, 2019). "Although none of these patients had diabetes requiring insulin, we do not have data on measures of insulin sensitivity." (PMID 31419965, 2019). "Furthermore, the previous study has found that STZ-induced diabetes markedly decreased lipid content and LDL receptors amount in epididymal WAT, which can be corrected to normal after insulin treatment." (PMID 31096578, 2019). "Lack of insulin or insulin resistance (IR) plays a central role in diabetes mellitus and makes diabetics prone to acute ischemic heart disease (AIHD)." (PMID 31300527, 2019). "We demonstrated diabetes-specific, long-term (but not short-term) recognition memory impairment and that this deficit was prevented by insulin or pyridoxamine treatment." (PMID 31451429, 2019). "DNA methylation from whole blood DNA was quantified using pyrosequencing at 5 CpG sites at the KCNQ1 locus in 510 individuals without diabetes from the ‘Relationship between Insulin Sensitivity and Cardiovascular disease’ (RISC) cohort." (PMID 30641161, 2019). "Generally, 90–95% of patients with diabetes are classified as having type 2 diabetes characterized by the lack of response to the effects of insulin by the human body or its inability to produce enough insulin." (PMID 31297092, 2019). "Except for the diabetes duration and use of insulin, patients with NPDR had a similar profile to those without DR." (PMID 31751306, 2019).
diabetes (continued). "The current diabetes classification into type 1 diabetes (T1D) and T2D is based on the ability to secrete insulin and the presence or absence of autoantibodies." (PMID 30837889, 2019). "The same study reported short-term improvements in diabetes-specific and generic health- related quality of life (HRQoL) related to insulin pump use that were not sustained." (PMID 31109342, 2019). "Classification and monitoring of diabetes has until recently relied primarily the on quantification of circulating glucose and insulin levels in combination with the presence or absence of autoantibodies." (PMID 30837889, 2019). "Type 2 diabetes mellitus (T2DM), affecting approximately 30 million Americans, is progressive: treatment intensifies as glycemic control declines, eventually leading to subcutaneous insulin therapy." (PMID 32685581, 2019). "Loss of these regular insulin oscillations is an early phenomenon in the development of insulin and non-insulin dependent diabetes mellitus." (PMID 31817135, 2019). "Although our results showed that insulin pens do not have superiority over insulin vials in controlling diabetes outcome in our sample, we cannot underestimate the patient preference for insulin pens." (PMID 31461470, 2019). "Unsurprisingly, given T2DM duration, preceding control, and preoperative insulin requirements, diabetes remission was not achieved in this case." (PMID 31072397, 2019). "Therefore, lack of data to estimate the effect on insulin sensitivity by gold standard techniques or on insulin or glucose metabolism after a meal challenge, which may be more informative for metabolic status and predicting diabetes risk." (PMID 31415611, 2019). "While this is an interesting in-silico experiment, such a therapy is currently clinically not possible as there are no “EPO pumps”, similar to the insulin pumps used for diabetes treatment, available." (PMID 31630225, 2019). "GLP-1 is thought to play an important role in treating diabetes and is a target of many therapeutics given its ability to stimulate the secretion of insulin, but not glucagon, in the pancreas." (PMID 31489910, 2019). "Most people indicative of having depression were of older age, females, below secondary level education, with a smaller family size, with low family income, using insulin, without a family history of diabetes and/or having an additional illness." (PMID 31181109, 2019). "Our analysis demonstrated that MSD alone cannot be successful without the provision of medications, especially insulin, and ongoing training for other medical personnel providing care to uninsured patients with diabetes." (PMID 31803710, 2019). "While neratinib is not at all selective for MST1, we believe that the underlying mechanisms of diabetes protection still derive from a direct protective effect on the β-cell mediated by MST1 and not from an effect on insulin sensitivity mediated by EGFR." (PMID 31676778, 2019). "It was noted that the prevalence rate of smoking among users of insulin was in fact lower than non-users of insulin in patients with type 2 diabetes mellitus in Taiwan." (PMID 31354621, 2019). "The following variables that were significant in the univariate analysis were included in the prediction model: presence or absence of DFU, income, duration of diabetes, use of a combination of insulin and oral medications, and smoking status." (PMID 31796044, 2019). "In people affected by diabetes insulin is either absent (type I diabetes) or not produced in the proper amount (type II diabetes)." (PMID 30893335, 2019). "Type 1 diabetes mellitus (T1DM) is due to lack of insulin hormone production from pancreatic β-cells, while type 2 diabetes mellitus (T2DM) results from ineffective insulin response." (PMID 32432227, 2019). "Diabetes is a chronic disease that occurs when the pancreas does not produce enough insulin or when the body cannot effectively use insulin, leading to raised glucose levels in the blood." (PMID 30602386, 2019).
diabetes (continued). "On the other hand, analysis of changes in glucose metabolism among 289 pre-DP diabetes without the use of insulin revealed that 173 (59.9%) had deteriorated glucose metabolism after DP." (PMID 29541399, 2018). "A small randomized clinical trial of only 40 patients with T2DM and established HF compared the effects of optimized diabetes treatment with insulin to no optimization for 4 months." (PMID 30343339, 2018). "The non-insulin users (75%, n = 158) were treated with non-insulin antidiabetic drugs (n = 74) or diabetes was controlled by diet and exercise only (n = 84)." (PMID 29486734, 2018). "Due to the beneficial effects of PESc on alloxan-induced diabetes and its potent antioxidant activity, we determined whether this extract would have any effect on in vitro INS-1E β cell culture proliferation and insulin secretion." (PMID 30046378, 2018). "In individuals without diabetes, the addition of fructose to diets in isocaloric exchange for other macronutrients does not affect hepatic fat content and insulin sensitivity." (PMID 29914103, 2018). "Moreover, the insulin level and HOMA-IR in the participants with previously diagnosed diabetes were higher than in those with NFG but lower than in the groups of newly diagnosed diabetes and IFG (P < 0.001)." (PMID 30211231, 2018). "We have evaluated older patients with diabetes treated in the Brazilian public healthcare system who already use high doses of insulin and have no adequate glycemic control for long periods." (PMID 29791677, 2018). "In diabetes, insulin fails to suppress hormone-sensitive lipase in adipose tissue and very low-density lipoprotein secretion in the liver leading to high circulating FAs." (PMID 29440374, 2018). "Compared to all other diabetes drugs, insulin does not have an upper dosage limit, and therefore, there is no level of hyperglycemia it cannot overcome." (PMID 29682315, 2018). "When the pancreas does not produce enough insulin or when the body cannot use insulin produced by the pancreas, diabetes can occur." (PMID 30539026, 2018). "The Wilcoxon sum of the ranks analysis was also used to look for enrichment of fatty acid saturation level amongst the highly ranked significant TAGs from comparison of tissue/diabetes-insulin sensitivity groups but no significance was detected." (PMID 29940972, 2018). "Independent predictors for intraoperative glycemia were: diabetes (non-insulinrequirement and insulin requirement), CPB time, and AXC (protective)." (PMID 29898149, 2018). "The improved GSIS despite decreased insulin+ area suggests that enhanced β-cell GCK expression improves glucose handling in HFD-induced diabetes through improved β-cell function rather than increased β-cell mass." (PMID 29915142, 2018). "IL-17 was produced in the PLNs of diabetic subjects but not healthy subjects when the PLN was exposed to diabetes specific antigens such as GAD65 or pro-insulin." (PMID 29963051, 2018). "In Israel insulin NPH is not used as basal insulin, so it seemed unwise to change their home insulin to insulin NPH without achieving a clear benefit in diabetes control." (PMID 30373567, 2018). "Twenty-five percent (n = 53) of the women with diabetes were treated with insulin, of which 18 combined insulin with non-insulin antidiabetic drugs." (PMID 29486734, 2018). "The development of diabetes mellitus after GDM was not related to any treatment they had during the gestational diabetes period (diet or insulin)." (PMID 30477103, 2018). "This conclusion is supported by the observation that low HOMA insulin sensitivity predicted incident diabetes mellitus, but low HOMA β-cell function did not." (PMID 29997193, 2018). "Two studies have described the change of insulin sensitivity after PIO treatment in less obese (but not real lean) diabetes patients." (PMID 29536426, 2018). "Even though none of the patients had diabetes or glucose intolerance, both G2 and G3 had higher glucose and insulin levels with lower Matsuda index (p<0.001)." (PMID 29466466, 2018).
diabetes (continued). "Thirdly, it is worth noting that the quantitative part of this study did not access the differences in preferences of participants based on the type of diabetes they have or the use/non-use of insulin as part of their treatment regimen." (PMID 30532235, 2018). "This study established that fasting plasma mannose was correlated with insulin sensitivity independent of BMI in Japanese individuals with diabetes." (PMID 30534205, 2018). "As well as in this paper, Xen amplifies the effects of GIP on insulin, glucagon, and pancreatic polypeptide release during graded glucose infusions in humans without type 2 diabetes mellitus." (PMID 29466430, 2018). "This is especially true of patients on insulin who get free instructions and monitoring kits at the diabetes centres, unlike patients in primary care." (PMID 29788908, 2018). "There is concern that diabetes and, more generally, aberrant insulin regulation, have a negative impact on brain function." (PMID 30054579, 2018). "Patients with diabetes mellitus were found to have achieved lower weight loss averages, as compared to those without diabetes and, among those with diabetes, patients who received insulin therapies had poorer outcome." (PMID 30400129, 2018). "With the combination of insulin and the LAG the blood glucose-lowering effect of insulin was prolonged, which could potentially be beneficial in diabetes treatment." (PMID 29558502, 2018). "Diabetes treatment regimens in DPN patients were changeable and cannot be correlated with sleep changes, and at the time of research, 10 patients were on different types of oral hypoglycemic drugs, 4 on insulin, and 6 on combination therapy." (PMID 30237691, 2018). "Additionally, regulation of renal insulin signaling pathway components and antioxidant enzymes are inspected in an animal model of streptozotocin (STZ)-induced diabetes." (PMID 30602713, 2018). "In this study, we sought to compare DPP-4 inhibitors with intermediate-acting NPH insulin in terms of effectiveness and safety for the management of patients with type 2 diabetes mellitus not controlled on metformin and sulfonylureas." (PMID 29713649, 2018). "Psychosocial barriers to successful insulin therapy in East Africa include lack of physician–patient interaction, understanding of diabetes and its treatments by both physicians and patients, and proper provision of testing and follow-up of patients." (PMID 29508275, 2018). "It seems the increased insulin level did not reduce the FBG of diabetes mice to the normal range at pre-treatment." (PMID 30199540, 2018). "Study population was adults with non-insulin-using type 2 diabetes mellitus who refused insulin therapy." (PMID 29904712, 2018). "AI subjects had higher rates of diabetes mellitus (AI 63.5% vs. non-AI 38.7% p=< 0.001) and were more likely to require insulin treatment of their diabetes mellitus (AI 36.5% vs. non-AI 17.2% p=< 0.001)." (PMID 30283862, 2018). "T1DM can only be treated with insulin, whereas patients with T2DM have a wide range of therapeutic options available, including lifestyle changes and administration of multiple oral and/or injectable anti-diabetes drugs, including insulin." (PMID 29409535, 2018). "Until recently it has been thought that insulin release is no longer functional in type 1 diabetes mellitus." (PMID 29416515, 2018). "Of this number, 3 were later withdrawn: 1 did not meet medical exclusion criteria (diabetes requiring insulin), and 2 returned their initial stool sample but did not complete a baseline survey and were lost to follow-up." (PMID 30425031, 2018). "In this study, however, GADA was measured in individuals with prevalent diabetes without insulin treatment within the first 3 years of diagnosis." (PMID 29589073, 2018). "For 16% of participants, their diabetes was managed by diet alone; 25% were using insulin at baseline (with or without other agents); and 58% were using hypoglycemic agents but not insulin." (PMID 29653635, 2018).